KRAS (KRas proto-oncogene, GTPase)
Diseases named in the same sentence as KRAS in open-access papers (continued):
Sharing a sentence is not in itself a finding about the gene and the disease.
cancer (continued). "Percent genomic alterations in COAD revealed a mutation frequency of 63% in APC gene and 38% in KRAS, making it as expected a highly WNT-activated and KRAS-driven cancer." (PMID 35664781, 2022). "From the GO ontology and KEGG pathways, the expression of KRAS plays an essential role in different stages of cancers with multiple functions." (PMID 36330448, 2022). "In view of the glucose-dependent impact of VC, a potent cytotoxic impact of VC in KRAS-mutant cancer cells is observed mostly at a low glucose cell culture condition." (PMID 36359850, 2022). "Progress in adoptive cell therapy enables immune cells to be armed with robust multi-weapons that recognize and kill cancer cells expressing mutant KRAS–specific neoantigens, thereby overcoming immune evasion, low efficacy, and specificity hurdles." (PMID 35014625, 2022). "In particular, KRAS-driven cancers show upregulated glycolysis, as well as altered glutamine utilization and mitochondrial function." (PMID 36048281, 2022). "Combined with previous results, DX2, protected by HSP7027, appears to promote cancer cell proliferation via the stabilization of oncogenic factor, KRAS, and via the inhibition of tumor suppressor p14ARF." (PMID 35546148, 2022). "KRAS is the predominant isoform of the RAS family proteins activated by mutations (most frequently at codon 12, 13, and 61) in cancers and is responsible for 85% of all RAS-driven cancers, particularly pancreatic, colon, and non-small cell lung cancer (NSCLC)." (PMID 35039048, 2022). "Here, we used a slightly different approach, monitoring cell viability following depletion of RADIL and IPO7 in KRAS mutant, KRAS WT, and normal human cancer cell lines." (PMID 35839996, 2022). "Owing to several mutations, the oncogene Kirsten rat sarcoma 2 viral oncogene homolog (KRAS) is activated in the majority of cancers, and targeting it has been pharmacologically challenging." (PMID 35163234, 2022). "A major challenge for such a treatment strategy is that macropinocytosis is a universal cellular process that exists in both KRAS mt cancer cells and normal cells." (PMID 35154489, 2022). "Recently, KRAS has been shown to be regulated by non-coding RNAs (lncRNAs, miRNAs and circRNAs) in the context of cancer development." (PMID 36077521, 2022). "The involvement of KRAS in glucose and the energy metabolism of cancer cells is well established and there is growing evidence linking mutations in KRAS and aberrant PI3K/AKT/mTOR pathway activity." (PMID 36497428, 2022). "This study explores the molecular relationships between KRAS genes and cancer, which is crucial for developing new biomarkers and effective prevention and treatment of tumors." (PMID 36330448, 2022). "Cellular inhibitor of protein phosphatase 2A, by inhibiting protein phosphatase 2A, helps to maintain MYC phosphorylation at Ser 62, thereby ensuring its cooperation with oncogenic KRAS in driving cancer progression." (PMID 36581205, 2022). "KRAS-driven cancers also recycle metabolites through increased autophagy or macropinocytosis to meet their increased demand for metabolites." (PMID 35681624, 2022). "The powerful synergistic impact of the VC and ATO combination was observed to effectively kill selected KRAS-mutant cancer cells and was recently reported." (PMID 36359850, 2022). "Efforts to utilize KRAS and related genes as targets to explore drugs for cancer have been undertaken for years, and inhibitor drugs to block KARSG12C have been developed." (PMID 36330448, 2022). "They render KRAS constitutively active, thus fueling the cancer cell with strong mitogenic, survival, stemness, invasive and pro-metastatic signals." (PMID 36010567, 2022).
cancer (continued). "The top four mutated genes in pediatric cancers were NRAS (1.8%), KRAS (0.9%), JAK2 (0.3%), and CREBBP (0.3%), highlighting that these genes should be analyzed further to assess the clinical significance of these mutations." (PMID 36497424, 2022). "Conversely, ranking cell lines based on their KRAS-axis activation showed the opposite result with relative resistance to probes targeting many classic cancer targets (e.g., Parbendazole)." (PMID 35013227, 2022). "We performed in vitro experiments, confirming the effectiveness of MEK inhibitor on the KRAS-mutated OVCAR-5 cell line, and the constitutively activation of MAPK cascade in RAS-mutated carcinoma." (PMID 35328764, 2022). "Our results showed that the high level of KRAS expression in carcinoma cells was due to an antiferroptotic effect, from which carcinoma cells respond to a low dose of erastin-induced ferroptosis." (PMID 35422066, 2022). "A BRAF point mutation in V600E is commonly reported in KRAS wild-type PDAC, and targeting BRAF_V600E is already being applied to various carcinomas, including PDAC." (PMID 36505826, 2022). "In cases of cancer, both mTOR and KRAS intersect the PKM2 nullcline in a stable state, where each of the three components has high activities." (PMID 33925206, 2021). "Our data suggested that IN10018 exerts therapeutic effects on multiple KRAS mutant cancer models, providing us a solid empirical basis and set of models for elucidating the biological connections between FAK signaling and KRAS activity." (PMID 34151545, 2021). "KRAS4B (hereafter simply referred to as KRAS) is the most prevalent RAS isoform in cancer, with its oncogenic mutants found in ~80% of all RAS-dependent tumors, especially in 98% of pancreatic, 45% of colorectal and 31% of lung tumors." (PMID 34680072, 2021). "G4 structures are often found in oncogene promoters, such as the KRAS oncogene and on the ends of telomeres suggesting the G4 structures are important in cancer progression and telomere maintenance." (PMID 34680084, 2021). "Although mTOR is a well-known inhibitor of autophagy-dependent survival in physiological conditions, many recent studies have revealed that autophagy becomes hyper-active in KRAS mutant cancer cells." (PMID 33925206, 2021). "This was based on an in vitro screen of 32 cell lines that represented lung, colorectal, head and neck, and genitourinary cell lines and identified Midostaurin as a potential radiosensitizer for KRas mutant cancers." (PMID 34733787, 2021). "The GSEA results showed that multiple cancer-related pathways were significantly associated with ISM1, including EMT, hypoxia, the KRAS signaling pathway, angiogenesis, the Notch signaling pathway, and the Hedgehog signaling pathway." (PMID 34350177, 2021). "We further investigated the effect of KRAS or BRAF knock-down on anchorage independent growth in these cancer-derived cell lines." (PMID 33793658, 2021). "As such, novel avenues are open for impacting KRAS-mediated cancers beyond the recent successes with covalent G12C modulation." (PMID 35024121, 2021). "The three isoforms of Ras oncoproteins, HRAS, KRAS, and NRAS, are frequently mutated in a variety of human cancers." (PMID 33580066, 2021). "For example, researchers have found that HRASV12 expressing cancer cells are electively sensitive to ferroptosis, and KRAS silencing in KRAS mutant Calu-1 cells strongly reduces erastin sensibility." (PMID 34568341, 2021). "In a variety of KRASG12C, KRASG12V, and KRASG12D cancer lines, MP-3995 blocked pERK signaling in the low micromolar range, thus demonstrating this molecule is a pan-KRAS inhibitor." (PMID 35024121, 2021).
cancer (continued). "The data imply that treatment of PDAC and, by extension, of other KRAS mutant cancers will require inhibition of KRAS and concurrent activation of immune pathways suppressed by cancer." (PMID 33674596, 2021). "In fact, it is now appreciated that the competitive fitness of KRAS mutant cancer cells is achieved through continuously tuning the mutant and WT allele product in a context-specific manner." (PMID 34573384, 2021). "We then discuss how EMT plays a role in the discordant response to drugs targeting KRAS mutant cancers, and the possible ways to overcome it." (PMID 34680229, 2021). "Targeting undruggable intracellular proteins with peptides: novel on-target macrocyclic peptide inhibitors of KRAS with broad inhibition of proliferation of multiple KRAS-dependent cancer cell lines." (PMID 35024121, 2021). "One possible reason for the imperfect response comes from the heterogeneity among KRAS mutant cancers." (PMID 34680229, 2021). "BI-3406 is a potent and selective inhibitor of the SOS1-KRAS interaction that attenuates reactivation by MEK inhibitors and enhances the sensitivity of KRAS-dependent cancers to MEK inhibition in preclinical models." (PMID 35083149, 2021). "More recently, CRISPR-Cas9 screening technology has been applied to loss-of-function genetic screening, enabling the complete knockout of target genes, that has been useful in identifying essential genes in KRAS mutant cancer cells." (PMID 33777798, 2021). "Genetic mutations are well known to induce functional abnormalities of cancer-associated proteins, such as EGFR, KRAS and APC, resulting in cancer progression." (PMID 34202873, 2021). "Oncogene-addicted cancers, including KRAS mutant cancers, are known to be dependent on glutamine for their survival." (PMID 34680229, 2021). "Inhibition of FGFR1 in combination with trametinib treatment induced cell death in KRAS-mutant cancer cells." (PMID 34830951, 2021). "In epithelial-like KRAS-dependent cancer cells, the induction of EMT by EMT transcription factors such as ZEB1, Snail, and Twist resulted in resistance to KRAS depletion." (PMID 34680229, 2021). "Oncogenic KRAS signaling has been reported to affect glutamine transport, energy metabolism, and cancer cell proliferation through mTOR activation." (PMID 34003553, 2021). "Oncogenic KRAS (Kirsten rat sarcoma viral oncogene homolog) is present in approximately 30% of all human cancers." (PMID 34502416, 2021). "In human cancer cell lines, an increase in GLUT1 expression and glucose uptake was critically dependent on KRAS or BRAF mutations." (PMID 33420213, 2021). "In the present study, a mathematical model was built containing the main elements of the regulatory network in KRAS mutant cancer cells to explore the further possible therapeutic strategies." (PMID 33925206, 2021). "For instance, PIK3CA, KRAS and BRAF harbored 1457, 805 and 707 driver mutations from pan-cancer cohorts, respectively." (PMID 33179738, 2021). "Very recently initial results of Sotorasib, a KRAS G12C inhibitor, in lung, colorectal and other types of cancers have been published." (PMID 34781949, 2021). "In silico calculations predicted that oncogenic KRas inactivation is a key factor for metabolic switching between mitochondrial and glycolytic metabolism in cancer." (PMID 35069209, 2021). "This is a limit and a missed opportunity to observe the complete KRAS cancer cells “plasticity” during the time." (PMID 33854968, 2021).
cancer (continued). "The need of cancer cells for glutamine, the so called “glutamine addiction”, represents a vulnerability that can be exploited therapeutically, especially in KRAS-driven cancers." (PMID 34485382, 2021). "The interaction between DARPins and KRAS involves the α3 and α4 helices, impedes KRAS dimerization, and has a suppressive effect on mutant KRAS-driven cancer cells." (PMID 34680951, 2021). "The KRAS (p.Q61R) mutation is also a known hotspot mutation that causes hyperactive KRAS/MAPK signaling and is frequently observed in cancers." (PMID 34156985, 2021). "However, KRAS or BRAF gain-of-function mutations are frequently observed in multiple cancer types, especially in CRC, pancreatic cancer, and non-small-cell lung cancers (NSCLC), which may hijack the function of SHP2 as the key mediator of multiple RTKs to control the ERK and AKT signaling." (PMID 34790119, 2021). "Möhrmann et al97 made use of next‐generation sequencing and droplet digital PCR techniques to analyse EV‐associated DNA (evDNA) obtained from the plasma of cancer patients with BRAF, KRAS or EGFR mutations." (PMID 33145869, 2021). "Recently, dasatinib was shown to enhance the sensitivity of KRAS mutant cells to trametinib (MEK1/MEK2 inhibitor) in different cancer types, including H23 and H358 NSCLC cell lines." (PMID 33495411, 2021). "This suggests that in particular cancers, for KRAS, BRAF, and NRAS, the major drivers of oncogenesis are gene mutations rather than cellular mRNA levels." (PMID 33398072, 2021). "In this study, FKBP4, ADCY9, and KRAS were differentially expressed in cancer tissues and adjacent normal tissues of LUAD and were related to the prognosis of LUAD." (PMID 33936178, 2021). "Regarding the last process, several studies achieved in different cancer cell models have shown that oncogenic KRAS promotes glucose uptake and its use through glycolysis, favoring the Warburg effect." (PMID 33670598, 2021). "These insightful reviews highlight the importance of disrupting the mechanism by which KRAS-mutant cancer cells subvert the surrounding cells to create a pathologic TME that fosters invasion, metastasis, and treatment resistance." (PMID 34771644, 2021). "Initial in vitro evaluations showed that IN10018 has moderate to good efficacy against KRAS mutant cancer cell lines; we confirmed significant inhibition of FAK activity for the examined cell lines." (PMID 34151545, 2021). "Among RAS proteins, KRAS is the predominantly mutated RAS isoform, comprising 85% of oncogenic RAS mutations in cancer cells." (PMID 34830024, 2021). "Moreover, KRAS mutations and non-METex14 alterations were found in 44% of cases, suggesting the companion mutations might be different across cancer types." (PMID 33403024, 2021). "TruSight Tumor 170 (TST170) is a next-generation sequencing (NGS) panel that covers 170 cancer-related genes, including KRAS, which is a key driver gene in CRC." (PMID 34640513, 2021). "Regardless of the histological and molecular characteristics, the growth and survival of the vast majority of cancer cells at primary and metastatic sites were dependent on the continuous expression of oncogenic KRAS." (PMID 34145248, 2021). "The finding that EFR3A recruits PI4KA and binds oncogenic KRAS suggests the possibility of targeting this signaling circuit at the level of the kinase for the treatment of KRAS-mutant cancers." (PMID 34504076, 2021). "IL-6 is crucial in KRAS driven PDAC development and progression from PanIn lesions to invasive cancer and promotes cell viability and invasion, underlining its metastatic potential." (PMID 32940862, 2021). "Studies highlighted in this review indicate a relatively strong therapeutic potential for the CRISPR systems in KRAS-driven cancers." (PMID 34781949, 2021). "Type I cancers include low-grade serous cancer, endometrioid cancer, mucinous cancer, and clear cell cancer, which harbor somatic mutations such as BRAF, KRAS and PTEN, often with microsatellite instability (MSI)." (PMID 34615547, 2021).
cancer (continued). "Corresponding to our biological system analysis, we propose the combined addition of pharmacologic ascorbate and chloroquine in KRAS mutant cancer treatment." (PMID 33925206, 2021). "The KRAS gene is an essential biomarker in cancer, mainly because it predicts the efficacy in therapies targeting the growth factor EGFR in tumors such as colorectal cancer." (PMID 34663841, 2021). "There are three individual RAS genes in humans, KRAS, NRAS, and HRAS, three primary sites mutated in human cancers, G12, G13, and Q61, and six possible amino acid substitutions at each site arising from a point mutation." (PMID 33998997, 2021). "Mutations in the WNT (e.g. APC or CTNNB), EGFR (e.g. KRAS, PIK3C or BRAF) and TGF-β (e.g. SMAD4) signalling pathways gradually render cells independent from niche signals to grow autonomously and promoting cancer." (PMID 33594337, 2021). "This approach was tested in cell lines where we showed the effective genotyping of a KRAS cell line and in the plasma of cancer patients, thus demonstrating its ability to diagnose precisely the mutational status of a patient." (PMID 34854867, 2021). "Patients with KRAS mutant cancers, however, underwent a longer treatment duration in the human trials." (PMID 34371702, 2021). "Overall, 34 specimens harbored driver mutations in five cancer genes (EGFR, PIK3CA, KRAS, CTNNB1, and MET), which are canonical driver mutations." (PMID 33407425, 2021). "HRAS, NRAS and KRAS, collectively referred to as oncogenic RAS, are the most frequently mutated driver proto-oncogenes in cancer." (PMID 34485382, 2021). "Mechanistically, gemcitabine-induced metabolic reprogramming and cancer stemness are regulated by ROS-mediated activation of the KRAS/AMP-activated protein kinase (AMPK) pathway." (PMID 33941245, 2021). "In KRAS-mutant subgroups, cancer tissue with lower expression of SDPR was accompanied with less infiltration of γ T cells and resting mast cells but higher abundance of plasma cells, CD4+ memory activated T cells and M1 macrophages." (PMID 33435990, 2021). "This is one example of a success story of targeting downstream effectors of KRAS for cancer therapy." (PMID 33801965, 2021). "Although the KRAS proto-oncogene point mutation occurs in 90% of PC, the unique activities of EGFR were demonstrated to promote cancer progression even when KRAS is mutated in PC cell lines." (PMID 33937024, 2021). "Since mutant KRAS has been shown to interact with NFκB-activating kinases promoting cancer cell survival and drug resistance, it is important to examine the potential role of mutant KRAS in regulating the levels and/or ratio of proBDNF/mBDNF." (PMID 34209215, 2021). "Meanwhile, in patients with KRAS G12A and G12V mutant cancers, the degree of PD-L1 expression was similar to the ORR and PFS in patients treated with ICIs." (PMID 35070984, 2021). "These class 3 (‘two-hit gain’) drivers include EGFR (2/3 cancer types), KRAS (4/16), and BRAF (1/6)." (PMID 34862370, 2021). "Taken together, these results suggest that cancer peptides targeting mutant KRAS should be included in the standard of care of all PCa patients, but before this, carefully designed combination therapies need to be performed." (PMID 33672917, 2021). "Once the initial evaluation took place, the nanoMIPs were tested for their efficacy to phenotype cancer cells by detecting KRAS protein in cell culture." (PMID 34854867, 2021).